PLK1 (polo like kinase 1)
Diseases named in the same sentence as PLK1 in open-access papers (continued):
Sharing a sentence is not in itself a finding about the gene and the disease.
tumor (continued). "PLK1 expression was higher in tumours from patients with metastases than from those with localised diseases (P < 0.05)." (PMID 37648284, 2023). "Intracerebral injection of CRISPR-LNPs against PLK1 into glioblastoma resulted in up to ~ 70% gene editing in vivo, leading to tumor cell apoptosis, a 50% reduction in tumor growth, and a 30% improvement in survival." (PMID 37814270, 2023). "It is worth mentioning that BI-2536, a potent inhibitor of PLK1, has been reported to promote tumor growth by stabilizing Myc." (PMID 37978524, 2023). "Apart from the overall level, we also analyzed the incidence of AEs based on tumor type and Plk1 inhibitor category." (PMID 36845678, 2023). "Given that the two closely related polo-like kinases, Plk2 and Plk3, are proposed to play tumor suppressor roles, the Plk1-specific inhibitory activity is an important property of Allopole-A." (PMID 37603740, 2023). "This also demonstrates that PLK1 affects the tumor immune microenvironment by suppressing immune infiltration." (PMID 37744268, 2023). "Polo‐like kinase 1 (PLK1), a serine/threonine‐protein kinase, functions as a potent oncogene in the initiation and progression of tumor." (PMID 36951624, 2023). "Depleting PLK1 can significantly inhibit tumour cell proliferation in vitro and induce tumour cell apoptosis." (PMID 37664042, 2023). "Dysregulation of PLK1 has been documented in various tumor types, contributing significantly to tumor development and progression." (PMID 38234395, 2023). "The final results indicated that PLK1 is a potent prognostic biomarker for LA and that PLK1 probably inhibits tumor immune infiltration and thus promote proliferation and metastasis of LA cells through inhibiting necroptosis." (PMID 37744268, 2023). "The importance of PLK1 in regulating mitosis has led to the successful development of a number of specific PLK1 kinase inhibitors aimed at retarding tumor growth." (PMID 37698938, 2023). "Collectively, RGCC/PLK1/AMPKα2 signal axis-mediated oxidative phosphorylation and fatty acid oxidation is critical for cell survival of disseminated tumor cells in lung, thereby facilitating pulmonary-tropic metastasis." (PMID 38102722, 2023). "The LHNP treatment led to a 60.4% decrease in PLK1 expression in the tumor site and significantly inhibited tumor growth and prolonged the median survival time from 29 days (saline treated) to 40 days in tumor-burdened mice." (PMID 37485250, 2023). "Researchers have become interested in studying urothelial tumours because of the regulatory role of PLK1 in a variety of tumours." (PMID 37664042, 2023). "The fusion of CASF with liposomes improved the transfection efficiency of the Lip/pDNA binary complex, reduced the expression of PLK1 protein, and improved the inhibitory ability of the Lip/pDNA complex on tumor cells." (PMID 38140096, 2023). "BRCA prognosis, clinical stage progression, and tumor classification were all shown to be substantially correlated with PLK1 expression." (PMID 36951624, 2023). "It was shown that the system blocked the PLK1 gene in addition to its effect on tumor growth and reduced toxicity, which demonstrated the synergistic effect of drug and siRNA combination against castrate-resistance PCa." (PMID 37842237, 2023). "Efficacy studies were performed in U87‐cell‐based subcutaneous tumors, and as per the results, a 23.5% decrease in tumor volume was observed in the mice given iRGD‐modified PLK1‐2‐targeted LHNPs." (PMID 37166046, 2023). "The results revealed that this formulation had long-term blood circulation with tumour accumulation ability and inhibited PLK1 protein production and tumour growth." (PMID 36771161, 2023).
tumor (continued). "Initially, DIO2 showed a mild positive correlation with PLK1 in normal lung samples, but this correlation intensified significantly (smaller p value) in tumor samples." (PMID 37988371, 2023). "After screening these compounds for activity against tumoral cell lines, the researchers found ON-01910 to be a potent inhibitor of the mitotic kinase Plk1, inducing mitotic arrest of tumor cells." (PMID 37111716, 2023). "Our study found that the combined knockdown of UBE2C with PLK1 significantly inhibited tumor cellular proliferation and triggered more lethal apoptosis and cell cycle arrest, compared to those of the knockdown of either alone." (PMID 37958642, 2023). "Research has shown that inhibiting PLK1 can promote the reactivation of latent infection state EBV and promote tumor cell death caused by EBV infection." (PMID 38037110, 2023). "The Angiopep-2 peptide was included as the targeting ligand, and consequently, the Cas9 RNP nanocapsule showed effective GBM tissue targeting (11.8% ID/g) and efficient Plk1 gene editing in the tumor (28.6% indel by Sanger sequencing) in a GBM mouse model." (PMID 37485250, 2023). "The results showed effective knockdown of the PLK‐1 gene in melanoma and inhibition of tumor growth in vitro and in vivo." (PMID 36925702, 2023). "In the present study, we for the first time found that PLK1 inhibition disrupted global DNA methylation and elevated the expression level of tumor suppressor genes." (PMID 37788997, 2023). "Several PLK1 inhibitors including volasertib (BI6267) have shown encouraging results for a range of tumours, including in vitro efficacy against HCC." (PMID 37648284, 2023). "This suggests that PLK1 significantly suppresses the immune function of LA patients, which also sets the stage for tumour growth and metastasis." (PMID 37744268, 2023). "PLK1 is highly expressed in multiple tumors and promotes tumor cell proliferation and cell transformation, and is associated with clinical stages and invasion." (PMID 37185598, 2023). "In HCC, PLK1 is overexpressed and elevated PLK1 levels correlate with reduced survival, tumour thrombus, metastasis, clinical stage, tumour stage, and histological grade." (PMID 37648284, 2023). "PLK1 overexpressing tumors (most epithelial cancers) have been shown to have minimal tumor infiltrates alongside low MHC-I expression." (PMID 36551637, 2022). "Experimental research has demonstrated that PLK1 acts as a tumor inhibitor when integrated with certain oncogenes (APCmin) in CRC cells, and patients with low PLK1 expression have a poor prognosis." (PMID 35484177, 2022). "We then explored the relationship between tumor antigens (CCNE1, PLK1, and SERPINA1) and ICD risk score using Pearson correlation analysis." (PMID 36393842, 2022). "In line with this assumption, IHC analysis of patient samples showed that PLK1 expression in CRC tumor biopsies was much higher than that in normal tissues." (PMID 34718347, 2022). "al. reported that they had complexed the up-conversion nanoparticles with CRISPR-Cas9 system targeting tumor gene polo-like kinase-1, and successfully turned on the gene editing using NIR light in 293T cells." (PMID 35277177, 2022). "The expressions of PLK1 in the 70 OSCC tissues showed a significant correlation with patients' tumor stage and size (P < 0.05)." (PMID 35756492, 2022). "Further analysis showed that the correlated genes of MTHFD family genes were enriched in several tumor progression-related pathways such as Aurora B pathway, PLK1 pathway, and cell cycle pathway." (PMID 35693982, 2022). "The CPTAC database of UALCAN online tool was used to explore the differential expressions of PLK1 proteins in tumor and normal tissues." (PMID 36618405, 2022).
tumor (continued). "Overexpression of PLK1 has been demonstrated in many tumor types, including BC, and its expression correlates with higher pathological grade, stage, recurrence and metastasis." (PMID 35456552, 2022). "In particular, tumors with elevated expression of PLK1 displayed lower immune activity, such as lower expression of Human Leukocyte Antigens (HLA), fewer B cells, NK cells and tumor-infiltrating lymphocytes and reduction of T-regulatory cells." (PMID 35719948, 2022). "This platform inhibited tumor cell apoptosis and proliferation by tumor−specific silencing of PLK1 and allowed for the non−invasive assessment of in vivo delivery efficiency by imaging tumor response." (PMID 36234452, 2022). "This system can deliver the CRISPR/Cas9 to bind with target gene Polo-like kinase 1 (PLK-1), which was a prosurvival gene overexpressed in the most tumors with antiapoptosis effect, resulting the significant effects of gene silence and tumor recession." (PMID 36431072, 2022). "The various new functions of PLK1 in many different cellular pathways suggest potential new combination approaches aimed at target tumor cell vulnerabilities/hallmarks (for example, with immunotherapy)." (PMID 35719948, 2022). "Accordingly, the combination of PD-L1 blockade with PLK1 inhibition significantly reduces tumor burden and prolongs survival of lung tumor-bearing mice." (PMID 35871223, 2022). "The potential antitumour activity of PLK1 inhibition was further corroborated in our study by the decreased cell proliferation and induction of apoptosis in treated tumour cells under matching in vitro conditions." (PMID 36054794, 2022). "Polo-like Kinase 1 (PLK1) is widely considered to be a proto-oncogene due to its increased expression in multiple tumor types, as well as its crucial role in regulating mitosis." (PMID 34561554, 2022). "Western blot analysis of the tumor tissue lysates showed greater PLK1 inhibition and cleaved caspase-3 induction in the combination group than abemaciclib alone." (PMID 35008374, 2022). "Volasertib, a PLK1 inhibitor, can significantly inhibit tumor growth and prolong the survival of animals in intracranial xenograft models." (PMID 36618405, 2022). "Further comprehensive analysis revealed that the expression of BCL2, LEF1, PLK1, and BNIP3 was correlated with tumor mutation burden, microsatellite instability, drug sensitivity, and pathology stage." (PMID 35251139, 2022). "Among the 32 tumor types, PLK1 gene alteration frequency was the highest in UCEC cases (>5%), and the “mutation” type was dominant." (PMID 36618405, 2022). "Conceivably, the induction of endogenous ERα signalling upon PLK1 inhibition is accompanied by DNA damage, which was previously shown to induce differentiation in other tumour models, as well as in normal keratinocytes." (PMID 36008466, 2022). "After the expression of PLK1 is reduced, the proliferation of tumor cells is inhibited, and apoptosis occurs, thus preventing the occurrence and development of tumors and improving prognosis." (PMID 35756492, 2022). "Polo-like kinase 1 (PLK1) is a member of the well-conserved serine/threonine kinase family and is essential for tumor cell division and proliferation." (PMID 36267311, 2022). "We also showed that overexpression of SETD3 promoted tumor cell migration, whereas inhibition of PLK1 activity compromised these phenotypes." (PMID 35912180, 2022). "Overall, TCGA data analysis confirms the significance of PLK1 overexpression in tumor tissue compared to normal (p = 4.22 × 10−20) and its elevated expression in TNBC when compared with Luminal A cells and tissues." (PMID 34561554, 2022). "Tumor cells display many cell fate variations after exposure to antimitotic agents, including PLK1 inhibitors." (PMID 35745782, 2022). "Two tumor antigens, namely, CCNE1 and PLK1, were associated with poor prognosis and infiltration of antigen-presenting cells." (PMID 36393842, 2022).
tumor (continued). "We observed that 15 out of 18 pair tissues displayed simultaneously increased SETD3 and PLK1 levels in tumor samples compared to their corresponding adjacent samples." (PMID 35912180, 2022). "In vivo studies showed that targeted delivery of Cas9/minicircle sgPLK1‐2 using LHNPs successfully edited the PLK‐1 gene in U87 subcutaneous xenograft tumor and intracranial tumor after IV injection and inhibited tumor growth." (PMID 37323878, 2022). "Then we further analyzed the correlation between the expression levels of PLK1 mRNA and prognosis in specific tumor types." (PMID 36618405, 2022). "We demonstrate that HMN-214 significantly inhibits NB growth in both 2D and 3D tumor models, probably by directly inhibiting PLK1 and other molecular targets." (PMID 35631350, 2022). "PLK1 dysregulation has been reported in different tumor types, contributing to tumor development and progression." (PMID 35719948, 2022). "Pharmacological inhibition of PLK1 can reduce tumor volume and induce tumor cell death in solid and hematologic malignancies." (PMID 34561554, 2022). "The data illustrated that the content of PLK1-4 rose in tandem with rising tumor grades, confirming our prediction." (PMID 35256538, 2022). "In this study, two genes (ANGPTL4 and PLK1) of the IGSPP that we constructed were involved in the regulation of the tumor cell cycle." (PMID 35581376, 2022). "IHC results showed that the combination of exogenous proline and cisplatin significantly reduced the staining of PLK1 in A549/CDDP tumour xenograft compared with their individual effects." (PMID 35910374, 2022). "Consistent with human OSA, these preliminary data outline the prognostic value of c‐Myc expression in cOSA and highlight the potential role of PLK1 as an antiproliferative therapeutic target for tumours overexpressing c‐Myc." (PMID 36054794, 2022). "In terms of immune microenvironment, we found that the expressions of AURKA, CCNA2, CCNE1, CDK1, CHEK1, and PLK1 were negatively correlated with tumor immune infiltrating cells." (PMID 36483630, 2022). "PLK1 is related to tumor aggressiveness and patient prognosis of non-small cell lung cancer (NSCLC)." (PMID 36311939, 2022). "To assess the effects of PLK1 inhibition on already-formed tumours, we injected SUM149PT cells or transplanted patient-derived xenografts (PDX) models into the mammary fat pads of NSG mice." (PMID 36008466, 2022). "By comparing and analyzing the significantly down-regulated genes in dormant tumor cells with MYC_TARGETS_V1, MYC_TARGETS_V2, three significantly down-regulated genes were obtained: Ccna2, Mad2L1 and Plk1." (PMID 35305591, 2022). "In parallel, RT-qPCR detection demonstrated the transcription levels of CHMP4A, HMGB1 and PLK1 were increased in tumor tissues compared to normal ones." (PMID 36267972, 2022). "PLK1 is frequently considered an oncogenic protein due to its essential role in driving cell division in tumor cells." (PMID 34775484, 2022). "Analysis of Plk1 expression in samples of HCC patients assured that Plk1 expression levels are higher in tumor cells than the normal liver tissue." (PMID 36080304, 2022). "Although HDAC inhibitors and PLK1 inhibitors have been extensively studied, their proposed mechanism(s) of action have been tumor centric." (PMID 35237663, 2022). "PLK1 is an important mitotic kinase that is overexpressed in LC-promoting oncogenesis and tumor metastasis." (PMID 35163777, 2022). "Various studies have demonstrated the effects of PLK1 inhibition on tumor inhibition of proliferation and ultimately, apoptosis." (PMID 34561554, 2022). "Spearman analysis indicates a potential positive monotonic relationship between miR-183-5p and PLK1 mRNA in normal breast tissue, but far less so in tumor tissue." (PMID 34561554, 2022).
tumor (continued). "Overall, our results confirmed that HMN-214 inhibits NB proliferation in both 2D cell cultures and 3D spheroid tumor models in a dose-dependent manner by inhibiting the cell cycle progression and inducing apoptosis by inhibiting the phosphorylation of PLK1." (PMID 35631350, 2022). "In the French cohort from Centre Antoine Lacassagne, Plk1 overexpression is higher in patients who relapsed after cisplatin and radiotherapy treatments which strongly suggests an important role during tumor genesis and progression." (PMID 34646387, 2021). "Polo Like Kinase 1 (PLK1) is a key regulator in mitosis and cytokinesis while it is highly expressed in most human tumor cells." (PMID 34925510, 2021). "Plk1 depletion or 5‐Aza alone slightly decreased tumor growth, but Plk1 depletion plus 5‐Aza resulted in an almost complete block of tumor growth." (PMID 34051063, 2021). "As a serine/threonine kinase, PLK1 is overexpressed in a variety of human tumors and induces tumor progression." (PMID 33500714, 2021). "In contrast to the “pro-tumor” oncogenic potential of PLK1, there is strong evidence for PLK1 also acting as a tumor suppressor." (PMID 34065956, 2021). "PLK1, the prototype member, is essential during mitosis and closely related to cellular proliferation and tumor growth." (PMID 34830902, 2021). "This diverging role of PLK1 reflects best the role of tumor heterogeneity and highly dynamic tumor change during growth and progression as well as during treatment." (PMID 34065956, 2021). "Here, we show that combined treatment with fibroblast growth factor receptor 1 (FGFR1) and polo‐like kinase 1 (PLK1) inhibitors evoke synergistic cytotoxicity in KRAS‐mutant tumor models in vitro and in vivo." (PMID 34369083, 2021). "To further confirm this combination effect in vivo, we next examined the anti‐tumor efficacy of combination treatment with a PLK1 inhibitor and oxaliplatin in a DLD1‐derived xenograft mouse model." (PMID 34881526, 2021). "The siRNA/Ap-CS efficiently knocks down the expression of Plk1 mRNA and PLK1 protein and exhibits the higher ability to induce the apoptosis of tumor cells than commercial transfection reagent lipofectamine 3000." (PMID 34006888, 2021). "Another oncogenic mechanism of PLK1 is targeting metabolic pathways in order to establish a tumor-adapted and growth-favoring cellular metabolism." (PMID 34065956, 2021). "The iRGD-containing nanoparticles showed efficient genome editing in human brain tumor U87 cells and GS5 cells on PLK1 gene, and effectively inhibited tumor growth in vivo." (PMID 33391496, 2021). "Genetic and pharmacological inhibition of PLK1 showed a strong combinatorial effect with oxaliplatin to block tumorsphere formation, indicating the critical role of PLK1 in tumor‐initiation capability." (PMID 34881526, 2021). "The Plk1 inhibitor volasertib inhibits a variety of carcinoma cell lines and induces tumor regression in several experimental tumor models." (PMID 33547392, 2021). "We verified the increased RNA expression of MMEJ-related H2ax, Fen1, Cdk1, Plk1, and Polθ and decreased RNA expression of Mdc1 in the MmuPV1 tumor tissues by real-time RT-qPCR." (PMID 34343212, 2021). "A series of tumor-related genes, such as Ras, Myc and polo-like kinase 1 (PLK1), have been verified and used in clinical trials." (PMID 34876145, 2021). "On the other hand, polo-like kinase 1 (PLK1) is a tumor-promoting factor and its overexpression is correlated with an increase in PC growth and induction of chemoresistance." (PMID 34943856, 2021). "The LACP nanoparticles enabled the efficient knockout of Plk-1 gene in melanoma tumors and significant tumor inhibition both in vitro and in vivo." (PMID 34683943, 2021).